TRAJ24 (T cell receptor alpha joining 24)
Gene: T-cell receptor joining (J) gene on chromosome 14 (22,519,969 to 22,520,031, forward strand). Ensembl gene ENSG00000211865.
Diseases named in the same sentence as TRAJ24 in open-access papers:
TRAJ24 is named in the same sentence as 3 diseases in open-access papers, as found by Europe PMC text mining. Sharing a sentence is not in itself a finding about the gene and the disease. The quoted sentences say what the papers report.
narcolepsy (1 paper, 2019). A sleep disorder characterized by a tendency for excessive sleepiness during the day which occurs even after adequate sleep in the nighttime. "Our analysis of in vivo expansion of HCRT-reactive TRAJ24+ cells opens an avenue for further investigation of the autoimmune contribution to narcolepsy development." (PMID 31748512, 2019). "Here, we present evidence of in vivo expansion of DQ6-HCRT tetramer+/TRAJ24+/CD4+ T cells in DQ6+ individuals with and without narcolepsy." (PMID 31748512, 2019).
tumor (1 paper, 2023). "First, using 5’RACE on a mixed lymphocyte-tumor cell culture (MLTC), we identified TRDV1 5’-untranslated region (UTR) and complete coding sequence rearranged productively to TRAJ24." (PMID 38077312, 2023).
TRAJ24 also shares sentences with these, for which no sentence is quoted: influenza (1 paper).